VWA7 (von Willebrand factor A domain containing 7)
Synonyms: C6orf27; G7C; NG37
Tractability: Antibody: UniProt places it where antibodies can reach, with high confidence; UniProt predicts a signal peptide or a membrane-spanning region; its Gene Ontology location is reachable by antibodies, with medium confidence; the Human Protein Atlas places it where antibodies can reach.
Gene: Protein-coding gene on chromosome 6 (31,765,590 to 31,777,328, reverse strand). Ensembl gene ENSG00000204396.
Subcellular location: Secreted
Subcellular location (Human Protein Atlas): Cytosol; Plasma membrane; Predicted to be secreted
Gene Ontology:
Cellular component: extracellular region
Genetic constraint (gnomAD): Loss-of-function variants: 68 observed, 85.04 expected, observed/expected ratio (o/e) 0.8, 90% interval 0.66 to 0.98. The upper end of that interval is the gene's LOEUF score, 0.98, which puts it in group 4 of 6, group 1 being the genes least tolerant of losing a copy. Missense variants: 1,076 observed, 1,154.1 expected, observed/expected ratio (o/e) 0.93, 90% interval 0.89 to 0.98. Synonymous variants: 424 observed, 480.75 expected, observed/expected ratio (o/e) 0.88, 90% interval 0.81 to 0.96.
Homologues: Orthologues: chimpanzee VWA7 (99% identical), macaque VWA7 (95% identical), pig VWA7 (86% identical), dog VWA7 (84% identical), mouse Vwa7 (82% identical), rat Vwa7 (81% identical), rabbit VWA7 (80% identical), guinea pig VWA7 (68% identical), tropical clawed frog vwa7 (39% identical), zebrafish vwa7 (26% identical).
Diseases named in the same sentence as VWA7 in open-access papers:
VWA7 is named in the same sentence as 8 diseases in open-access papers, as found by Europe PMC text mining. Sharing a sentence is not in itself a finding about the gene and the disease. The quoted sentences say what the papers report.
schizophrenia (1 paper, 2020). A major psychotic disorder characterized by abnormalities in the perception or expression of reality. "VWA7 encodes Von Willebrand Factor A Domain-Containing Protein 7; previous global GWAS associated the VWA7 locus with IBD, blood plasma proteome, blood protein levels, and schizophrenia." (PMID 31932636, 2020).
VWA7 also shares sentences with these, for which no sentence is quoted: fatty liver disease (2 papers); cancer (1); cardiac arrhythmia (1); cardiac disease (1); metabolic disease (1); metabolism syndromes (1); nonalcoholic fatty liver disease (1).